IL1B (interleukin 1 beta)
Diseases named in the same sentence as IL1B in open-access papers (continued):
Sharing a sentence is not in itself a finding about the gene and the disease.
HIV-1 infection (59 papers, 1992 to 2025). The type species of lentivirus and the etiologic agent of acquired immunodeficiency syndrome (AIDS). "An investigation into single nucleotide polymorphisms (SNPs) within NLRP1, NLRP3, NLRC4, CARD8, CASP1, and IL1B genes revealed a significant association between two SNPs residing in NLRP3 and IL1B with increased susceptibility to HIV-1 infection." (PMID 38785555, 2024). "Also, IL-1β appeared decisive in the neuroinflammatory process associated with HIV-1 infection and was induced in human monocytes with subsequent inflammasome activation." (PMID 38138916, 2023). "Notably, Caspase-1 and IL-1β are associated with pryoptosis, or inflammation mediated apoptosis; pryoptosis is linked to progression of HIV-1 infection via CD4+ T-cell depletion." (PMID 32117283, 2020). "As expected, we observed donor-to-donor variation in the extent to which IL-1β secretion occurred following HIV-1 infection." (PMID 39229127, 2025). "In contrast, our findings suggest that Gag-Pol deletion or inhibition of PR activity only partially inhibited HIV-1-infection-induced NLRP1-mediated IL-1β secretion." (PMID 40920844, 2025). "Functional analyses reveal that IL1B activates NF-κB, thereby promoting productive HIV-1 infection while simultaneously suppressing viral spread, suggesting a natural latency reversing activity to deplete the reservoir in ART-treated individuals." (PMID 40442100, 2025). "Since we recently reported that human iMGs) are highly susceptible to HIV-1 infection, we next sought to look at the ability of HIV-1 icRNA to induce IL-1β release in iMGs." (PMID 40920844, 2025). "Among the pro-inflammatory cytokines tested, only IL-1β significantly increased upon HIV-1 infection in both MDM (p = 0.0210) and microglia (p = 0.0356) compared to mock infected." (PMID 38659061, 2024). "Upon HIV-1 infection of human microglia, pro-IL-1β is secreted at 4 h, and mature IL-1β is secreted at 24 h, accompanied by caspase-1 activation, initiating the inflammatory process." (PMID 39224601, 2024). "Active HIV-1 infection is required to activate this pathway, as when exposed to ARVs, induction of pro-IL-1β and release of IL-1β were decreased." (PMID 37027347, 2023). "We found that CARD8 KO THP-1 cells complemented with WT CARD8 underwent IL-1β secretion and cell death in response to both VbP and HIV-1 infection in a dox-dependent manner, confirming that HIV inflammasome activation is CARD8-dependent." (PMID 37417868, 2023). "At the protein level, we observed these M1 inflammatory factors (TNF-α, IL-1β, and IL-6) sustained the release to the supernatant during HIV-1 infection." (PMID 37798121, 2023). "Under the condition of glycolysis inhibition, we observed that the expression of M1 markers TNF-α, IL-1β, and IL-6 was also reversed, indicating that blocking glycolysis inhibits M1 polarization of macrophages driven by HIV-1 infection." (PMID 37798121, 2023). "On the other hand, IL-1β secretion following HIV-1 infection is strictly dependent on TLR priming, consistent with its established role for transcriptional upregulation of IL-1β." (PMID 37417868, 2023). "Although viral products are known to be associated with neuronal damage, the major cause of neurotoxicity observed with HIV-1 infection is through the innate immune system, induced by the release of proinflammatory cytokines such as TNF-α and IL-1β." (PMID 37631062, 2023). "Elevated proinflammatory cytokines, such as TNF-α, IL-6, and IL-1β, appeared in the plasma and lymph nodes from the early stage of HIV-1 infection." (PMID 38138916, 2023). "In contrast, the release of IL-1β after HIV-1 infection or VbP treatment was entirely dependent on TLR priming (right)." (PMID 37417868, 2023). "Expression of caspase-1, NLRP3, and IL-1β was increased in lymph nodes and bone marrow between day 1 and 3 after HIV-1 infection (mean fold change (FC) of 2.08, 3.23, and 6.05, p<0.001, respectively)." (PMID 36800238, 2023).
HIV-1 infection (continued). "High levels of pro-inflammatory cytokines, such as tumour necrosis factor alpha (TNFα), interleukin 6 (IL-6) and interleukin 1 beta (IL-1β) in both plasma and lymph nodes, are observed from the early stages of HIV-1 infection." (PMID 34112126, 2021). "HIV-1 can induce expression of IL-1β, which is associated with progression of HIV/AIDS, and in microglial cells HIV-1 infection resulted in overexpression of miR-146a." (PMID 32117283, 2020). "Since Meth was found to induce IL-1β and miR-146a expression, and these play important roles in immune regulation, we explored their effects on HIV-1 infection of CD4+ T-cells." (PMID 32117283, 2020). "Other studies in human monocytes have shown that HIV-1 infection-induced production of IL1β via the NLRP3 inflammasome-dependent mechanism(s)." (PMID 32784383, 2020). "HIV-1 infection of macrophages and microglia in the CNS leads to cellular activation and secretion of neurotoxic cytokines such as IL-1β and TNF-α." (PMID 33171974, 2020). "These experimental conditions allowed us to assess changes in IL-1β expression in baseline, enhanced, or diminished HIV-1 infection, respectively." (PMID 32117283, 2020). "Apart from the intrinsic upregulation of NF-κB transcription during HIV-1 infection, macrophage-derived inflammatory cytokines, IL-1β and TNF-α, are known to activate NF-κB signaling and induce a reactive astrogliosis phenotype in astrocytes." (PMID 33171974, 2020). "At day 1 of HIV-1 infection, we observed enhanced release of IL-1β, followed by increased IL-1β mRNA and miR-146a expression at day two." (PMID 32117283, 2020). "The inflammasome activation ends with the active forms of IL-1β and IL-18 that are increased during HIV-1 infection, promoting disease progression." (PMID 29963050, 2018). "Our findings indicate that the presence of risk Vs of APOL1 is permissive of HIV-1 persistence in human podocytes in synergy with IL-1β, a cytokine that characterizes the inflammatory milieu of acute and chronic phases of HIV-1 infection." (PMID 27599995, 2016). "Recently, increased secretion of bioactive IL-1β was observed to be relevant for inflammatory programmed cell death (pyroptosis) of CD4pos T cells with abortive HIV-1 infection." (PMID 27599995, 2016). "The inflammatory milieu that characterizes HIV-1 infection both at systemic and tissue levels can enhance this pathologic loop via the IL-1β priming." (PMID 27599995, 2016). "Future studies using proposed inflammasome inhibitors, including anti-IL-1β therapies such as anti-human monoclonal antibodies and IL-1 receptor antagonists, which have been used successfully to treat Cryopyrin-associated syndromes, might also be suitable for treating HIV-1 infection." (PMID 24886384, 2014). "HIV-1 infection induced pro-IL-1β in human microglia at 4 hr post-infection with peak IL-1β release at 24 hr, which was accompanied by intracellular ASC translocation and caspase-1 activation." (PMID 24886384, 2014). "Further suggesting a role for NLRP3 for control of HIV-1 infection, polymorphisms in genes for NLRP3 and the inflammatory cytokine IL-1β are both associated with increased susceptibility to HIV-1 infection." (PMID 23435233, 2013). "NLRP3 sensing of HIV-1 has been suggested based on finding that IL-1β is upregulated during HIV-1 infection of human DCs." (PMID 23435233, 2013). "Milk from two of these subjects contained high levels of multiple pro-inflammatory cytokines including TNFα, IL-1β, IL-6, IL-8, MIP-1α, MIP-1β, MCP-1 and IP-10, and enhanced cell-associated HIV-1 infection at dilutions as high as 1∶500." (PMID 22952771, 2012). "During HIV-1 infection in the brain, proinflammatory cytokines such as IL-1β and tumor necrosis factor (TNF)-α are released by infiltrating HIV-1 infected macrophages." (PMID 23029125, 2012).
HIV-1 infection (continued). "Our data also simulate the conditions seen in Human Immunodeficiency Virus 1 (HIV-1) infection, where IL-1β expression is up-regulated through activation of the NLAP3 inflammasome." (PMID 23164507, 2012). "In both case, the result is a high level of pro-inflammatory cytokines, such as tumor necrosis factor alpha, interleukin 6 and interleukin 1 beta, right from the early stages of HIV-1 infection." (PMID 21362195, 2011). "Previous studies have also linked HIV-1-infection-induced inflammasome activation to CARD8 expression in macrophages and demonstrated that pyroptotic cell death and IL-1β secretion either required NNRTI-induced dimerization of Gag-Pol or Gag-Pol overexpresison and subsequent PR activation." (PMID 40920844, 2025). "Furthermore, HIV-1 infection induces a notable release of proinflammatory cytokines, namely IL-1β and IL-18." (PMID 39224601, 2024). "HIV-1 infection prompts inflammasome activation in microglia, leading to the release of IL-1β, which could contribute to inflammation and neuronal death, potentially leading to complex neurobehavioral deficits." (PMID 38785555, 2024). "Studies using primary human microglia showed that IL-1β was released after HIV-1 infection." (PMID 37189617, 2023). "Here, substantial increases in TNFα, IL-8, and IL-1β were observed after HIV-1 infection." (PMID 35132117, 2022). "Notably, increased IL-1β expression and down regulation of IFN stimulated genes, including TRAF6, are associated with enhanced HIV-1 infection and replication." (PMID 32117283, 2020). "Association of IL-1β and IL-8 to Ng expression in context of HIV-1 infection was evaluated in the presence or absence of neutralizing antibodies against these cytokines." (PMID 29703241, 2018). "Interestingly, IL-1β and IL-6 enhance HIV-1 infection in monocytes and resting CD4+ T cells in vitro." (PMID 25785697, 2015). "HIV-1 infection enhanced expression of topoisomerase IIβ, IL-1β and COX-2." (PMID 21887247, 2011). "As expected, HIV-1 infection induced expression of IL-1β, IL-6, TNF-α and CXCL8." (PMID 20877724, 2010). "It is also possible that IL-1β release after HIV-1-dependent CARD8 activation after HIV-1 infection could contribute to pathogenesis since IL-1β induces the differentiation of Th17 cells, a highly HIV-susceptible CD4+ T cell subtype, as well as the recruitment of other target immune cells." (PMID 37417868, 2023). "Finally, to directly establish the role of IL-1β in modulating CCR5 expression via miR-103 in the context of HIV-1 infection, we pretreated MDMs with the Supnt alone or in the presence of either neutralizing anti-IL-1β, anti-TNF-α, or a combination of both antibodies (Abs)." (PMID 32994328, 2020). "In this study, we demonstrate that establishing productive HIV-1 infection and cytosolic viral icRNA expression activates NLRP1 inflammasome and IL-1β secretion in macrophages and iMGs." (PMID 40920844, 2025). "Similar to our observations with VbP, we found that IL-1β secretion, cell death, and CASP1 activation (as measured by FLICA assay) were significantly reduced in CARD8 KO versus WT THP-1 cells following HIV-1 infection." (PMID 37417868, 2023). "HIV-1 infection is required for activation as, when exposed to ART, induction of pro-IL-1β and release of IL-1β were decreased." (PMID 32596261, 2020). "Here, we demonstrate that HIV-1 infection decreases the level of Ng in human FC tissues in HAD patients and this decrease is in part due to overexpression of proinflammatory cytokines IL-1β and IL-8." (PMID 29703241, 2018). "The increased expression of IL-1β, IL-18 and caspase-1 observed herein among brains from HIV-1 infected persons was highly indicative of inflammasome activation during HIV-1 infection, prompting further investigation of this possibility." (PMID 24886384, 2014).
HIV-1 infection (continued). "As several inflammasome components were induced in the brain during HIV-1 infection, the ability of HIV-1 to activate inflammasome-dependent IL-1β release was explored using primary human microglial cultures." (PMID 24886384, 2014). "A number of pro-inflammatory cytokines (TNF-α, IL-1β, IL-6, IFN-γ) and oxidative stress markers (such as nitric oxide) are known to be elevated during brain HIV-1 infection." (PMID 24884548, 2014). "Since the derogatory effects of opioids on HIV-1 infection have been widely reported, it is possible that the HIV-1 induced increase in IL-1β secretion can also increase MOR expression in astrocytes, as suggested by our data." (PMID 23164507, 2012). "Compared to mock-infected MDM, HIV-1 infection significantly inhibited phagocytosis of opsonised IE without altering MDM viability, and decreased secretion of IL-6 and IL-1β." (PMID 22363802, 2012). "Moreover, BV is associated with increased levels of proinflammatory cytokines (e.g. IL-1β and IL-8) and these cytokines induce the secretion of other proinflammatory cytokines or recruit other immune cells, thus possibly increasing the number of cells permissive for HIV-1 infection." (PMID 19419540, 2009). "Because blood–brain barrier damage and impaired cerebral perfusion are common features of HIV-1 infection, we evaluated the role of tumour necrosis factor-α (TNF-α) and interleukin-1β (IL-1β) in mediating disruption of the blood–brain barrier." (PMID 18475460, 1992). "HIV-1 infection did not modulate IL-1β secretion by endothelial cells, but co-infection increased its secretion in the BBB model (1.4- and 1.8-fold increase compared to Mtb mono-infection for Mtb/Bal and Mtb/VSV-G co-infections, respectively)." (PMID 40420159, 2025). "In conclusion, IL-1β production decreased in all the PWH groups, likely due to HIV-1 infection." (PMID 40936922, 2025). "In addition, it has been shown that HIV-1 infection engages the NLRP3 inflammasome complex, however the mechanisms that regulate IL-1β and/or IL-18 have remained mostly unexplored." (PMID 33861800, 2021). "TEA and benzamil were successful in inhibiting IL-1β secretion but did not inhibit IL-18 upon HIV-1 infection." (PMID 33861800, 2021). "The expression level of IL-1β and IL-6 remained below the threshold of detection in MF supernatants even after HIV-1 infection, and the level of TNF-α mRNA was not modified upon infection." (PMID 32365752, 2020). "Many studies have previously reported a correlation between the observed increase in the production of pro-inflammatory cytokines IL-1β, IL-6, IL-18 and TNF-α; and IFN inducible chemokines CXCL9, CXCL10 and CXCL11 during the course of HIV-1 infection and the up regulation of HIV-1 replication." (PMID 29373606, 2018). "In response to opsonised IE, HIV-1 infection significantly reduced IL-6 release (1,116 pg/mL (IQR: 352–3,387) compared to 1,552 pg/mL (IQR: 889–6,331); p = 0.0078) and IL-1β release (16 pg/mL (IQR: 7–21) compared to 33 pg/mL (IQR: 27–65); p = 0.0078) from mock-infected IFNγ primed MDM." (PMID 22363802, 2012). "IL-1β along with TNF-α is known to reactivate latent or non-productive HIV-1 infection of astrocytes in an NF-κB dependent manner." (PMID 22027397, 2011). "IL-1β along with TNF-α is also known to reactivate latent or non-production HIV-1 infection of astrocytes in an NF-κB dependent manner." (PMID 22027397, 2011). "Macrophages release various inflammatory cytokines such as IL-1β and TNF-α upon HIV-1 infection." (PMID 19404407, 2009). "We observed that IL1B increased NF-κB activity ~4-fold regardless of HIV-1 infection status." (PMID 40442100, 2025). "However, neither HIV-1 infection nor VbP alone led to an increase in IL-1β levels (right, no prime condition), consistent with prior reports." (PMID 37417868, 2023). "Additionally, it is unknown whether HIV-1 infection activates other P2X7 signaling pathways, notably those involved in the NLRP3 inflammasome, which mediates IL-1β release." (PMID 26635799, 2015).
HIV-1 infection (continued). "Typical features of HIV-1 infection of the brain are the occurrence of multinucleated giant cells and microglial nodules; immunohistochemical examination of the brains of SIV-infected macaques identified an enrichment of IL-1β immunopositive cells in these lesions." (PMID 24886384, 2014). "However, IL-1β is elevated in the brain tissues of patients infected with HIV-1, is upregulated and secreted by infected/activated immune cells in the proinflammatory setting of HIV-1 infection, and induction of the IL-1β autocrine loop leads to further production of IL-1β and other cytokines." (PMID 22027397, 2011). "Thus, HIV-1 infection alone (i.e. in the absence of molecules causing premature dimerization of Gag-Pol) is sufficient to induce cell death in THP-1 cells, and priming (e.g. via TLR stimulation) is required for HIV-1 infection-induced IL-1β secretion and elevated levels of cell death." (PMID 37417868, 2023). "Elevated IL-1β is observed in HIV-infected patients, although these studies do have not directly link HIV-1 infection to inflammasome activation." (PMID 26635799, 2015). "While HIV-1 infection establishment was unaffected upon treatment with PR inhibitors, both DAR and LOP pretreatment reduced, but did not completely abrogate IL-1β secretion in HIV-1/WT-infected MDMs, while having a negligible impact on IL-1β secretion in HIV-1/ΔGag-Pol-infected MDMs (respectively)." (PMID 40920844, 2025).